IFITM3 (interferon induced transmembrane protein 3)
Diseases named in the same sentence as IFITM3 in open-access papers (continued):
Sharing a sentence is not in itself a finding about the gene and the disease.
influenza (continued). "Furthermore, data from mice infected with a high dose of the virus suggest that the downregulation of IFIMT1 and IFITM3 might be involved in severe influenza pathogenesis." (PMID 35708622, 2022). "Moreover, recent clinical investigations in humans have linked increased susceptibility to influenza with specific single nucleotide polymorphisms (SNPs) in genes coding IFITM1 and IFITM3 (Everitt and others 2012; Zhang and others 2013; Allen and others 2017; Kim and others 2020, 2021)." (PMID 35708622, 2022). "Overcoming this obstacle, we recently reported that mice lacking the interferon-induced transmembrane protein 3 (IFITM3) suffer from severe cardiac electrical dysfunction and fibrosis upon influenza virus infection, thus providing a long-sought model for influenza-associated cardiac complications." (PMID 35544568, 2022). "To address the fundamental question of whether severe lung and systemic inflammation alone is sufficient to induce cardiac dysfunction, we turned to an animal model, specifically IFITM3 KO mice, which serve as a severe infection model to study influenza-induced cardiac dysfunction." (PMID 35544568, 2022). "Similarly, for IFITM3 SNP analyses, the non-risk rs12252-T/T homozygous allele was observed in 91% of influenza+ patients (remaining were C/T heterozygous) and 100% of influenza- patients, whereas the risk C/C homozygous allele was absent." (PMID 33976217, 2021). "In addition, IFITM3 has also been shown to be induced, in DCs, after influenza infection, in mice, and is involved in migration of these cells to lymph nodes and consequent activation of influenza-specific lymphocytes." (PMID 32754450, 2020). "Therefore, HIV-1-induced enhancement in IFITM3 levels in macrophages may not only restrict influenza life cycle in this cell, but could also prevent influenza-induced pro-inflamatory cytokine release." (PMID 24978204, 2014). "From the PBMCs of influenza- and COVID-19–infected patients, MSC identified 2 platelet subpopulations expanded in patients with severe COVID-19—namely, CRBN/RBX1-high (M33) and IFITM3-high (M34) cells." (PMID 41066207, 2025). "Interferon-induced transmembrane protein 3 (IFITM3) is a key antiviral protein that prevents the fusion of enveloped viruses with host cell membranes, thereby inhibiting infections such as influenza, dengue, and Zika." (PMID 41462343, 2025). "From the PBMC of influenza and COVID-19 infected patients, MSC identified two platelet subpopulations expanded in severe COVID-19 patients, namely, CRBN/RBX1-high (M33) and IFITM3-high (M34) cells." (PMID 39764102, 2024). "Our human and mice analyses indicate a direct influence of influenza infection on the regulation of bulk IFITM1 and IFITM3 expression in vivo." (PMID 35708622, 2022). "Another IFITM3 SNP rs34481144 identified in the 5 ‘UTR of the IFITM3 gene was reported to decrease the transcription level of its mRNA and the CD8+T cell number in the airways of influenza-infected individuals." (PMID 35769480, 2022). "Platelets and MKs upregulate IFITM3 (transcript and/or protein) upon infection in human (dengue, influenza, and SARS-CoV-2) and in vitro; overexpression of IFITM3 in MKs was sufficient to prevent dengue infection." (PMID 36524131, 2022). "Among them, some had greater significance for influenza infection than others, such as IFI27 (also called ISG12) and IFITM3 (both are up‐regulated genes), have been reported widely and in details." (PMID 33448094, 2021). "However, with exception for the IFITM3 rs12252 polymorphism, we could not pinpoint specific genetic polymorphisms to be associated with severe influenza infection in a pooled meta-analysis." (PMID 34930124, 2021). "However, the comparison group were not ILI non hospitalized Influenza A(H1N1)pdm09 positive patients, meaning that they did not test the hypothesis that the IFITM3 rs12252 variant was involved in the severity of the Influenza infection." (PMID 27351739, 2016).
influenza (continued). "Others have identified genes that are protective during influenza infection, including MX1, NCR1, CCR5, IFITM3 and IL1014." (PMID 27156515, 2016). "In addition, the IFITM3 rs34481144 C > T change disrupts the methylation site, and T carriers have reduced CD8+ T cells in their airways during natural influenza infection." (PMID 37323564, 2023). "Using a high-dose murine model of infection, we confirmed not only the downregulation of IFITM1 but also of IFITM3 in the lungs of mice with severe influenza, as opposed to humans." (PMID 35708622, 2022). "The miR-targeted virus induced fewer cardiac conduction irregularities and significantly less fibrosis in mice lacking interferon-induced transmembrane protein 3 (IFITM3), which serve as a model for influenza-associated cardiac pathology." (PMID 35544568, 2022). "Another limitation was the lack of analysis of the genetic variation of IFITM1 and IFITM3 genes and experimental assays of viral inhibition by these genes in specific conditions of infection with influenza A and SARS-CoV-2 virus." (PMID 35708622, 2022). "No impact of IFITM3 genotype in boosting influenza specific antibodies in young adults within 1 year after receiving seasonal influenza vaccination was observed." (PMID 29868492, 2018). "In this study, we show that influenza replication is attenuated during HIV-1/A(H1N1)pdm09 co-infection experimental assays, as HIV-1 viral particle or its viral surface glycoprotein gp120 reduce A(H1N1)pdm09 replication in an IFITM3-dependent fashion." (PMID 24978204, 2014). "Considering the lack of connection between the genotypes and IFITM3 expression, we further noted that IFITM3 transcript levels, in our respiratory specimens, were not correlated with influenza viral load nor with clinical status of the influenza cases." (PMID 32754450, 2020). "Furthermore, as IFITM3 can restrict the replication of influenza viruses, we evaluated the correlation between IFITM3 levels and influenza viral load, regardless of the genotype." (PMID 32754450, 2020). "Furthermore, IFITM3 levels were comparable in the distinct clinical groups and were not correlated with influenza viral load in analyzed samples." (PMID 32754450, 2020). "We did not observe any differences in the level of boosted influenza antibody responses among young adults carrying different IFITM3 genotypes within 1 year after receiving seasonal influenza vaccination, and antibody levels remained at a protective level particularly against influenza A virus." (PMID 29868492, 2018). "Thus, in contrast to influenza infection, IFITM3 did not influence the infection efficiency of MCMV in our assays." (PMID 28240600, 2017). "HeLa cells transfected with siRNA for IFITM3 (or with its scrambled control; Scr) were infected with A(H1N1)pdm09, exposed to HIV-1 or culture medium, and, 24 h after influenza infection, cell supernatants and monolayers were harvested to quantify influenza and IFITM3 levels, respectively." (PMID 24978204, 2014). "Hence, in a small subgroup of our influenza cohort from which we could obtain a second sample of PBMCs at intensive care unit (ICU) discharge, we analyzed longitudinal dynamic patterns of IFITM1 and IFITM3 expression and their relationship with the incidence of relevant in-hospital complications." (PMID 35708622, 2022).
COVID-19 (87 papers, 2020 to 2026). A disease caused by infection with severe acute respiratory syndrome coronavirus 2. "COVID-19 mortality was associated with the IFITM3 rs6598045 GG and AG in the Delta variant and the IFITM3 rs6598045 AG in the Alpha variant." (PMID 40429912, 2025). "The IFITM3 rs6598045 G allele was significantly more common in deceased COVID-19 patients than in those who recovered." (PMID 40429912, 2025). "Polymorphism in IFITM3 has been associated with COVID-19 and severity, and its expression inhibits COVID-19 infection." (PMID 41066207, 2025). "Analysis of a Chinese COVID-19 patient cohort demonstrated that the rs12252 C genotype of IFITM3 is associated with the SARS-CoV-2 infection risk in the studied cohort." (PMID 40429912, 2025). "Patients with the IFITM3 rs12252 (C) allele had a higher risk of COVID-19 mortality than those with the T allele in Chinese and Caucasian populations." (PMID 38793616, 2024). "In comparison, a third G allele of IFITM3 rs12252 was significantly associated with hospitalization and mortality in COVID-19 patients in a large Arab population, particularly in the younger population." (PMID 38793616, 2024). "Polymorphism in IFITM3 has been associated with COVID-19 and severity, its expression inhibits COVID-19 infection and these suggest M34 is a protective platelet subtype under pro-inflammatory environments." (PMID 39764102, 2024). "For instance, genotyping of cytokine-related single-nucleotide polymorphisms (SNPs), e.g., IL-6 rs1800796, IL-10 rs1800896, TNF-α rs1800629, and IFITM3 rs12252, has shown them to underlie the differential viral virulence and severity of COVID-19." (PMID 38400050, 2024). "This study aimed to determine the relationship between IFITM3 gene rs34481144 polymorphism and clinical parameters with COVID-19 mortality." (PMID 37323564, 2023). "In conclusion, the IFITM3 rs34481144 gene polymorphism was linked to COVID-19 mortality, and the SNP rs34481144 CT variation in both sexes and rs34481144 TT exclusively in women were related to COVID-19 mortality." (PMID 37323564, 2023). "In conclusion, IFITM3 rs34481144 gene polymorphism was linked to the mortality of COVID-19, with the rs34481144-T allele being especially important for mortality." (PMID 37323564, 2023). "In the future, it will be essential to find out if IFITM3 rs34481144 gene polymorphism can accurately be linked to COVID-19." (PMID 37323564, 2023). "The mechanisms by which IFITM-3 rs12252 with the G allele is associated with COVID-19 deterioration are not completely understood." (PMID 38155729, 2023). "Logistic regression analysis was applied to analyze the association between ACE-2 and IFITM-3 genetic variants, IL-6 profile, and COVID-19 severity." (PMID 38155729, 2023). "A meta-analytic study involving more than four studies from England, Italy, and Spain showed a significant association of the IFITM-3 rs12252/ACE-2 rs2285666 polymorphism with COVID-19 susceptibility." (PMID 38155729, 2023). "ACE-2 and IFITM-3 genetic variants are potential predictors of COVID-19 severity, critical outcomes, and post-COVID-19 complications." (PMID 38155729, 2023). "This confirmed the observation that IFITM3 rs34481144 T allele carriers were more likely to COVID-19 mortality, with the CC genotype acting as a protective factor." (PMID 37323564, 2023). "Recent clinical investigations have studied the connection between IFITM3 gene polymorphisms and COVID-19 susceptibility and severity; however, the results have been inconsistent." (PMID 37323564, 2023). "The genetic variant rs12252-C of IFITM3 is associated with more severe COVID-19, possibly by causing defects in the control of viral replication in cells." (PMID 37259108, 2023). "This study aimed to explore the association between ACE-2 and IFITM-3 genotypes and their corresponding allele frequencies with disease severity indices in the Egyptian COVID-19 population." (PMID 38155729, 2023).
COVID-19 (continued). "IL-6 levels together with ACE-2 rs2285666 and IFITM-3 rs12252 genetic variants were suggested here as significant predictors for COVID-19 fatality." (PMID 38155729, 2023). "COVID-19 mortality was associated with IFITM3 rs6598045 GG and AG in Delta variant and IFITM3 rs6598045 AG in Alpha variant." (PMID 36403064, 2022). "The C(G) allele in rs12252 IFITM3 was found to be a risk factor for hospitalization with COVID-19 in the European population." (PMID 35327350, 2022). "Based on our findings, the IFITM3 rs6598045 G variation was associated with an increased risk of death and hospitalization due to COVID-19." (PMID 36403064, 2022). "The severity of COVID-19 is linked to the IFITM3 rs12252, which is associated with the truncated form of the IFITM3 protein." (PMID 36403064, 2022). "IP-10 and MCP-1, MIP-α, IL-6, and CC genotype of rs12252 (42 T/C) SNP of IFITM3 gene are associated with COVID-19 severity." (PMID 35822078, 2022). "The analysis of a Chinese COVID-19 patient cohort indicates that the rs12252 CC genotype of IFITM3 is associated with the risk of acquiring SARS-CoV-2 infection and the weakened neutralizing antibody response." (PMID 36423162, 2022). "Analysis of a Chinese COVID-19 patient cohort demonstrates that the rs12252 CC genotype of IFITM3 is associated with SARS-CoV-2 infection risk in the studied cohort." (PMID 36423162, 2022). "A possible correlation was observed between the mortality rate of COVID-19, the G allele of IFITM3 rs6598045, and SARS-CoV-2 variants." (PMID 36403064, 2022). "We found a statistically significant association between the allele frequency of IFITM3 rs6598045 and the case mortality rate of COVID-19." (PMID 36403064, 2022). "Variants in the IFITM3 gene have been linked to changes in expression and the risk of severe Coronavirus disease 2019 (COVID-19)." (PMID 36403064, 2022). "The COVID-19 mortality rate in Delta variant was associated with the IFITM3 rs6598045 G allele in this study." (PMID 36403064, 2022). "We conducted a systematic review followed by meta-analysis including studies covering genetic association of COVID-19 susceptibility or prognosis with IFITM3, FURIN, ACE1, and TNF-α variants." (PMID 35432458, 2022). "Mention should also be made of the rs12252 polymorphism in the IFITM3 gene, for which the minor C allele was associated with susceptibility to COVID-19." (PMID 35327350, 2022). "Our results underline a potential role of IFITM3 in COVID-19, although mechanistic evidence will be decisive." (PMID 34424199, 2021). "Since COVID-19 vaccination efforts are well underway in most of the world, the antibody response to COVID-19 vaccination in IFITM3-rs-12252 allele carriers needs to be studied and corrective measures undertaken if needed." (PMID 34434219, 2021). "The role of the IFITM3-rs12252 allele in the higher morbidity and mortality from COVID-19 among African American and other ethnic minorities should be studied and better understood." (PMID 34434219, 2021). "In a study of hospitalized patient with COVID-19 in Beijing, China there was a significant association between homozygosity for the IFITM3-rs12252 allele and severity of COVID-19 and death." (PMID 34434219, 2021). "We performed log-linear regression analysis between the case fatality rate of COVID-19 and allele frequencies of the polymorphisms of the IFITM3, ACE2, TMPRSS2, and IL6 genes in several ethnic groups." (PMID 33396837, 2020). "In the present study, we identified a strong correlation between the case fatality rate of COVID-19 and the allele frequency of the rs6598045 SNP of the IFITM3 gene." (PMID 33396837, 2020). "The role of the examined IFITM3 variants in the severity of COVID-19 should be elucidated, by in vitro investigation of the effect of H1 (A_C), vs H2 (G_C), vs H3 (A_T) rs12252_rs34481144 haplotypes in SARS-CoV-2 infectivity and viral spread." (PMID 33240681, 2020).
COVID-19 (continued). "We identified a strong correlation between the case fatality rate of COVID-19 and the allele frequency of the rs6598045 SNP IFITM3 gene." (PMID 33396837, 2020). "A report showed that a single-nucleotide polymorphism rs12252 in IFITM3 gene was correlated with higher disease severity in COVID-19." (PMID 33253295, 2020). "Therefore, the aim of the current study was to investigate the association between the IL-6 rs1800796, IL-10 rs1800896, TNF-α rs1800629, and IFITM3 rs12252 polymorphisms and the presence of post-COVID symptoms in previously hospitalized COVID-19 survivors." (PMID 38400050, 2024). "Moreover, IFITM3 rs34481144 TT genotypes (OR 3.38, 95% CI 1.05–10.87, P < 0.0001) in women were significantly associated with COVID-19 mortality." (PMID 37323564, 2023). "Therefore, we aimed to determine the association between rs34481144 and rs12252 SNPs in the IFITM3 gene and humoral immune response after vaccination against COVID-19 with mRNA vaccines." (PMID 37515072, 2023). "Association studies of IFITM3 rs12252 with COVID-19 prognosis included in the systematic review." (PMID 35432458, 2022). "Moreover, data regarding polymorphisms in 8 genes (HLA, ABO, ACE1, ACE2, APOE, CCR5, TMPRSS2, and IFITM3) were meta-analyzed in relation to the risk of infection and severity of COVID-19." (PMID 35793369, 2022). "For example, rs12252, variant of IFITM3, was reported to be associated with severe COVID-19." (PMID 36531218, 2022). "Among other ISGs transcribed during COVID-19, IFITMs might be necessary, and some studies have linked the prevalence of SNPs affecting IFITM3 to COVID-19 susceptibility (Gómez and others 2021; Schönfelder and others 2021)." (PMID 35674675, 2022). "After adjusting for SARS-CoV-2 variants and IFITM3 rs6598045 genotypes, COVID-19 mortality was associated with IFITM3 rs6598045 GG (OR 35.16, 95% CI 8.49–145.54) and AG (OR 2.20, 95% CI 1.59–3.05) in Delta variant and with IFITM3 rs6598045 AG (OR 4.10, 95% CI 2.58–6.53) in Alpha variant." (PMID 36403064, 2022). "Moreover, a recent meta-analysis has confirmed that IFITM3 rs12252 SNP was associated with COVID-19 susceptibility." (PMID 36233516, 2022). "In fact, IFITM3 has been associated with COVID-19 severity and a higher cytokine storm." (PMID 36233516, 2022). "Single nucleotide polymorphisms in human IFITM3 known as ns12252 and rs34481144, which lead to IFITM3 loss-of-function, have been associated with severe outcomes following Influenza A virus infection as well as severe COVID-19." (PMID 33880473, 2022). "The IFITM3 rs12252 C allele was found in a statistically significant number of hospitalized participants with H1N1 influenza and Coronavirus disease 2019 (COVID-19)." (PMID 36403064, 2022). "In conclusion, the IFITM3 rs6598045 gene polymorphism was associated with COVID-19 mortality." (PMID 36403064, 2022). "In future, it will be crucial to determine whether the IFITM3 rs6598045 SNP is reliably associated with COVID-19 mortality." (PMID 36403064, 2022). "Further examination and screening for the IFITM3 dynamics in COVID-19 might explain the possible therapeutic and diagnostic options." (PMID 32595654, 2020). "Almost concurrently, the analysis of a cohort in Chinese COVID-19 patients proposed an association between the severity of the disease and the presence of the minor allele of rs12252 of the Interferon-induced transmembrane protein 3 (IFITM3) gene." (PMID 33240681, 2020). "Notably, we identified a strong correlation between the case fatality rate of COVID-19 and the allele frequency of the rs6598045 single nucleotide polymorphism (SNP) of the IFITM3 gene." (PMID 33396837, 2020). "The genetic variants of IFITM3 were associated with disease severity in COVID-19 patients." (PMID 33061814, 2020). "Similarly, the IFITM3 rs6598045 G allele in both genders was associated with COVID-19 mortality." (PMID 36403064, 2022).